CD4 (CD4 molecule)
Diseases named in the same sentence as CD4 in open-access papers (continued):
Sharing a sentence is not in itself a finding about the gene and the disease.
tumor (continued). "In agreement with our flow cytometry results, we identified a significant upregulation in several genes encoding for immune checkpoint inhibitory molecules (e.g. Pdcd1, Lag3, Ctla4, Icos, Tigit, Tnfrsf18) in tumor-infiltrating CD4/ALK4-KO CD4+ T cells, compared to WT CD4+ T cells." (PMID 34548096, 2021). "It is widely accepted that the simultaneous stimulation of both CD8+ and CD4+ T cells is the best strategy for therapeutic vaccination, since both cell types are required for a long-lasting immune response and can synergize to fight tumor cells." (PMID 33546283, 2021). "The top three largest fractions of immune cells were macrophage M2 (20%), CD4+ memory resting T cell (14%) and macrophage M0 (14%), which revealed that macrophages may play a potential role in tumor immunity." (PMID 35096572, 2021). "Thus, we demonstrated that the TCRs expressed on empirically expanded CD8+ (Pt3) or CD4+ (Pt 38) opT cells were sufficient to confer tumor-recognition ability in a patient-specific manner." (PMID 34789550, 2021). "In addition, we tested the requirement for the adaptive immune system by implanting B16 tumor cells into WT and Fats−/− mice subjected to antibody-mediated depletion of CD4+ or CD8+ T cells." (PMID 34262035, 2021). "One potential mechanism to overcome this limitation is to enhance the proportion of activated effector CD4+ T cells expressing GITR in the tumor microenvironment before administering GITR agonist to overcome the potential mechanisms of resistance generated by tumor cells." (PMID 34312483, 2021). "Therefore, we sought to profile the tumor-infiltrating CD4 + T cells, CD8 + T cells, and Treg cells." (PMID 34066839, 2021). "PD-L1 is expressed on the surface of various tumor cells and has the ability to bind to PD-1 receptors of CD4+ and CD8+ T Cells thus altering proliferation and cytokine production, leading to T cell inactivation and apoptosis of these important cellular players of adaptive immunity." (PMID 33562138, 2021). "However, many cancer cells have co-opted these checkpoint inhibitors in order to prevent their destruction by CD8+ and CD4+ tumor infiltrating lymphocytes (TILs)." (PMID 33912442, 2021). "Indeed, in both cases, almost 30% of CD4+ T-cells are FOXP3+ as compared to the normal levels of FOXP3+ Treg found in the spleen or in the tumor-draining lymph nodes." (PMID 33671179, 2021). "Additionally, the percentage of CD4+FOXP3+ Tregs in tumor tissues exhibited a significant positive association with L1CAM and CCL22 in patients with ESCC." (PMID 33710805, 2021). "Interestingly, CD4+ CD25+FoxP3+ Treg cells were decreased in tumor tissues from the B. longum 420 and anti-PD-1 antibody combination and B. longum 420-alone groups compared to the other groups." (PMID 34589578, 2021). "In addition, a high level of potassium released from necrotic tumor cells inhibits both CD4+ and/or CD8+ T lymphocyte activation." (PMID 34503283, 2021). "This anti-tumor activity is closely associated with the increase of tumor-specific T cells, the enhancement of CD4 + T cells and CD8 + T cell infiltration and the significant decrease of tumor resident CD4 + CCR8 + Treg." (PMID 34884642, 2021). "CD4 TILs also produced tumor necrosis factor (TNF)α that induced tumor cell senescence." (PMID 34201655, 2021). "The presence of TILs and high PD-L1 expression in the TME might be an indicator of impaired function of CD4+ and CD8+ T cells against tumor cells or might be associated with improved OS and PFS in EOC patients." (PMID 33804458, 2021). "Next, in an attempt to evaluate the immunostimulatory capacity of tumor-infiltrating CD4+ T cells exposed to activin-A in vitro, we cultured them along with autologous CD4+ T cells obtained from the periphery of the same patient (PB CD4+ T cells) upon polyclonal stimulation." (PMID 34548096, 2021). "The majority of CD4+ cells were CD3+, and thus they were likely tumor-associated CD4+T cells." (PMID 33968044, 2021).
tumor (continued). "Conventional T cells included conventional CD4+ T cells (cluster 4 in Paratumor and cluster 3, 8, 11 in Tumor; CD4+), regulatory T cells (cluster 8 in Paratumor, and cluster 5 in Tumor; FOXP3+), CD8+ T cells (cluster 2, 5, 10 in Paratumor, and cluster 0, 1, 2 in Tumor; CD8A+)." (PMID 33429363, 2021). "CD4+ naive T cells (cluster 0 and cluster 2) at the core of the tumor express more immune checkpoint molecules, such as CTLA4, which has been used in clinical practice, and LAG3, HAVCR2, and TNFRSF9/CD137, which are currently undergoing clinical trials than those at other locations." (PMID 34513820, 2021). "Indeed, PSGL-1 activation in the tumor microenvironment can promote CD4+ T-cell exhaustion pathways, which promotes tumor development." (PMID 34434194, 2021). "This is critical, as T cells are the most important orchestrators of the anti-cancer immune response, both through direct tumoral cell killing by cytotoxic T CD8+ cells, and through activation of anti-tumor immune responses with the help of T CD4+ helper cells type 1 (Th1)." (PMID 34884543, 2021). "Taken together, our data suggest that high salt-mediated ex vivo expansion of tumor-primed CD4+T cells could induce effective tumor specific anti-cancer responses, which may have a novel cell-based cancer immunotherapeutic application." (PMID 33918403, 2021). "However, CD4+T cells from non-tumor-primed spleens produced a diminished anti-cancer cell cytotoxicity." (PMID 33918403, 2021). "In this study, we found that higher expression of CD38TILs had lower percentage and absolute counts of CD3+ and CD3+CD4+ T cells, which suggested that CD38TILs might affect CD3+ and CD3+CD4+ T cells to promote tumor growth and metastasis." (PMID 34211854, 2021). "Furthermore, tEV plus SyBV treatment stimulated tEV antigen‐specific CTL responses with an increase in IFN‐γ, which is considered to be more essential than the role of CD4+ T cells for the substantive killing of tumour cells." (PMID 34262675, 2021). "At the tumor site, while CD4+ T cells may be the most frequently encountered T-cell population, their ability to proliferate in response to tumor antigens after DC-mediated pulsing was significantly diminished." (PMID 34944826, 2021). "CD4+ T cells are another major cell community that controls tumor growth." (PMID 33968780, 2021). "Moreover the positive correlation with the NUP62CL expression in LUAD of the infiltration level of the tumor infiltrating B lymphocytes and memory CD4+ T cells was exhibited by CIBERSORT." (PMID 33934535, 2021). "Additionally, NorCA can increase the secretion of Exos from HCC cells, and N-Exos play roles in regulating CD4+ cells during tumor progression." (PMID 34888230, 2021). "Furthermore, the decrease in the T-reg population within CD4+ cells is a complementary component of tumor growth inhibition." (PMID 34835178, 2021). "We performed TIMER database analysis to determine the correlation between the ten-IRG prognostic signature and tumor infiltration of six types of immune cells, namely B cells, CD4+ T cells, CD8+ T cells, macrophages, neutrophils, and dendritic cells in the TME." (PMID 33536348, 2021). "Importantly, we also demonstrated that anti-OX40 increased clonality in the peripheral blood CD8+ T-cell compartment and clonality of tumor-infiltrating CD4+ cells of some patients." (PMID 33594075, 2021). "Interestingly, we observed dysregulation of several ligands of T cell function genes in GBM tissue corresponding to the T-cell receptors that were dysregulated in tumor infiltrating CD4+ T-cells." (PMID 34012510, 2021). "The percentage of CD4+ FoxP3+ T cells was lower in the tumors treated with STINGa, implying that tumor-infiltrating Tregs might lose FoxP3 expression following STINGa treatment." (PMID 35008305, 2021).
tumor (continued). "Indeed, we found that Tox and Tox2 directly control the transcriptional regulation of Pdcd1 and Lag3 expression, largely determining the functional incompetence of tumor-infiltrating CD4+ T cells from CD4/ALK4-KO mice." (PMID 34548096, 2021). "Firstly, this facilitates the penetration of vascular disrupting drugs into the tumor area and, secondly, it may increase the recruitment of CD8+ and CD4+ T lymphocytes into the tumor." (PMID 34439079, 2021). "Indeed, in vitro, CD4+ CAR T cells were shown to exert cytotoxic activity against tumor cells, although at a lower level than CD8+ CAR T cells, but to produce more IFN-γ and TNF, and to proliferate more extensively upon contact with tumor cells." (PMID 33546283, 2021). "There was an association between inflamed (tumor, CD8) and the sign of cytotoxic and TH1 immune signature's effect size (Cytotoxic cells: p = 0.00012, TH1: p = 1.4e-06) and between inflamed (tumor, CD4) and the effect size of the TH17 signature (p = 0.007)." (PMID 33791196, 2021). "Therapeutic options depend on the extent and rate of tumor growth, VL, and CD4+ T lymphocyte count." (PMID 34812320, 2021). "Consistent with tumor antigen exposure, we observed increased frequencies of in vivo-stimulated MM CD4+CD69+ T cells, although exhibiting lower potential to respond to further in vitro polyclonal stimulation, thus indicating a dysfunctional phenotype of PB CD4+ T cells." (PMID 34502204, 2021). "As subsets of TILs have distinct roles in tumor immunity, we evaluated whether cryopreservation impacts the frequencies of CD4+ TILs, CD8+ CTLs, and CD4– CD8– TILs within total CD3+ TILs." (PMID 34067849, 2021). "These mice harbored increased numbers of TRM CD4+ cells compared to non-vaccinated mice, suggesting that the viral adjuvant to the cellular vaccination promoted tissue residence of CD4+ cells that could combat tumor recurrence." (PMID 34208864, 2021). "Importantly, infiltration of CD4+ and CD8+ T cells into the tumor has been associated with improved overall and progression-free survival in OvCa patients." (PMID 34248988, 2021). "Alspach and colleagues reported that activation of CD4+ T cells by MHC II molecules could play an important anti‐tumor role." (PMID 33783985, 2021). "Further characterisation has also shown the diversity of CD4+ T cell populations in NPC tumour." (PMID 34956172, 2021). "The RNA transcriptome revealed substantial differences between CD4+ T cells from tumor and blood of GBM patients in their RNA expression pattern: 341 genes with log2 fold change of 2 or more and p value < 0.01 were shown to be dysregulated in these cells in GBM relative to their expression in blood." (PMID 34012510, 2021). "p53110–124 specific CD4+ T cells promote the generation and function of tumor-specific CD8+ CTLs." (PMID 34805170, 2021). "Additionally, after treating prostate tumors with mHIFU, the ratio of CD8+:CD4+ cells in the spleen was also found to be increased, and protective against subsequent tumor challenges." (PMID 34136405, 2021). "In addition, both CD4+ and CD8+ T cells were significantly reduced in the spleen and CD4+ T cells were reduced in tumor-draining lymph nodes (LNs)." (PMID 33953170, 2021). "Gene set enrichment analysis of exhausted CD4+ T cells from plaque and tumor MF demonstrated the significant upregulation of the PD-1 ligation pathway, which is in agreement with prior analyses investigating the MF TME, further supporting BTLA to be a surrogate marker of exhaustion." (PMID 34885092, 2021). "Interestingly, the chemokine (C-X-C motif) ligand 13 (CXCL13), which is also known as a ‘B lymphocyte chemoattractant,’ was highly upregulated in the tumor compared to normal lung in both macrophages, CD4+ and CD8+ T cells." (PMID 33918618, 2021).
tumor (continued). "Interestingly, the selective ablation of B cells within the tumor abrogated therapy response and resulted in lower on-treatment CD4 + and CD8 + T cell tumor infiltration along with a lower representation of effector memory CD8 + T cell subsets." (PMID 33602280, 2021). "In other studies, T-cell receptor repertoires were assessed in total TIL populations, often isolated from FFPE samples, which does not distinguish the source of the TCR sequences found within the tumor (e.g., Tconv CD4+, Treg CD4+, CD8+, or natural killer T cells)." (PMID 33594075, 2021). "Moreover, approximately 77% of 35 tumours with a low expression of CD4+TILs had a high expression of CD204+TAMs whereas 23% of tumours had a low CD204+TAMs expression." (PMID 35201470, 2021). "However, increasing evidences have demonstrated that CD4+ T cells play an important role in generating and maintaining anti-tumor immune responses." (PMID 34702254, 2021). "It has been shown that the tumor microenvironment plays a central role in tumorigenesis development and progression, and the levels of tumor-infiltrating CD4+/CD8+ T cells, M1 macrophages, NK cells, and inflammatory cytokines directly influence the onset of immune priming and adaptive immunity." (PMID 34993195, 2021). "Tumor-primed CD4+T cells were obtained from the draining lymph nodes from tumor bearing mice." (PMID 33918403, 2021). "On the basis of these results, we hypothesize that the Apelin-induced CCL8 secreted by ECs provides a chemotactic signal to CD8+ and CD4+ T cells and promotes T cell extravasation from vessels and infiltration into the tumor." (PMID 34234274, 2021). "Moreover, CD4+ Th1 T-lymphocytes destroy tumor cells also trhough the secretion of cytokines and chemokines, especially interleukin 2 (IL2) and interferon-gamma (IFNγ), which help the recruitment of further NK cells, CD8+ T-lymphocytes and macrophages." (PMID 33920423, 2021). "In addition, protection of CD4+ T cells can be combined with other genetic modifications such as introduction of HIV- (or tumour-) specific CARs to facilitate anti-HIV or anti-cancer immunity." (PMID 34112993, 2021). "Additionally, recent evidence has shown CD4 T cells can acquire cytotoxic capabilities in the presence of IL-2 and mediate direct tumor cell killing." (PMID 34012443, 2021). "CD4+ T cells and Tfhs also play a prominent role in anti-tumor immunity." (PMID 33894748, 2021). "Indeed, to secrete IL-17A and recruit myeloid cells into the tumor in a mouse ovarian cancer model, CD4 T cells needs the expression of TNFR1." (PMID 33498483, 2021). "Naïve CD4+T cells (Th type 0, Th0) can be activated by the encounter with a tumour antigen via peptide/MHC class II TCR and differentiate into Th type 1 (Th1) and Th type 2 (Th2) cells, depending on the intensity of stimulation and presence of certain cytokines and other factors." (PMID 34073106, 2021). "Therefore, CD4+ T cells were most likely the key factor for NHE family to regulate tumor development in COAD." (PMID 34759967, 2021). "In addition, CD8/CD3 ratio was higher in RBM10 mutant group (P=0.019), and CD4/CD3 ratio was lower (P=0.001), which further proved that the fraction of anti-tumor T cells are higher in patients with RBM10 mutations." (PMID 34367963, 2021). "Interestingly, transfer of CD8+ T cells alone has shown to have low tumor free survival rates whereas transfer of both CD4+ TH1 cells and CD8+ CTLs has shown a synergistic anti-tumor response resulting in complete regression in 80% of mice." (PMID 34012451, 2021). "Interestingly, we discovered that in tumor-infiltrating CD4+ T cells Tox and Tox2 bind on the genetic locus of NFAT2, suggesting the existence of a positive feedback loop in the regulation of gene expression between NFAT2 and Tox." (PMID 34548096, 2021).
tumor (continued). "To understand the phenotypic transitions between the five transcriptional clusters of tumor-infiltrating CD4+ TC, we performed pseudotime ordering, which revealed that early activated Tconv cluster 0 split into three branches representing three distinct developmental states." (PMID 33602930, 2021). "Following pembrolizumab therapy, the TME of responders becomes activated, as evidenced by the increased immune activation gene score, increased frequency of ICOS+ and Ki-67+ CD4+ T cells, and a local enrichment of tumor cells with dendritic cells (CN-5) and CD4+ T cells (CN-8)." (PMID 34795254, 2021). "Also, a tumor microenvironment skewed in favor of a CD4 + T helper 1 (Th1) effector T cell infiltration is conditional for the response of castration resistant prostate cancer metastasis to anti-CTLA-4." (PMID 33602280, 2021). "Likewise, nuclear localization of NLRP3 was observed in TOX+ CD4+ T cells isolated from tumor lesions." (PMID 34220814, 2021). "Having ruled out the cytotoxic effectors, we hypothesized that increased CD4+ T cell tumor infiltration is key to the antitumor response in Batf3–/– mice." (PMID 34283809, 2021). "It has been demonstrated that epigenetic modulation of CD4+ T cells polarization at tumor site might influence cancer patients’ outcome." (PMID 34262562, 2021). "Collectively, these findings support a chemoattractant mechanism for the sustained clinical response to pembrolizumab therapy observed in CTCL responders: upregulation of CXCL13 in tumor cells attracts effector PD-1+ CD4+ T cells, promoting successful antitumor activity." (PMID 34795254, 2021). "However, the percentage of Foxp3+ cells in CD4+ T cells was increased in the spleen, blood, and tumor tissue by 15%–50% in mice treated with BLM (P < 0.05)." (PMID 34378880, 2021). "In this study, we used xCell to analyze infiltrating immune cells in a tumor and through the univariate and multivariate Cox analyses screened out two prognosis-related immune cells, CD4+TN and common lymphoid progenitor (CLP), which were used to construct a Cox model and figure out the risk-score." (PMID 34777388, 2021). "Thus, we identified various receptors that were upregulated in each lineage specific CD4+ subpopulation and then analyzed their ligand expression status in on the tumor cells." (PMID 34012510, 2021). "Tumour-derived TGFβ induces Foxp3+ Tregs conversion from its CD4+CD25− precursors." (PMID 33941245, 2021). "However, CD4+ T cells were also shown to bear cytolytic abilities and were proposed by a number of studies to represent the major anti-tumor T cell subpopulation." (PMID 34440139, 2021). "Tumor-infiltrating CD4+ cells consisted of FOXP3+CD127− Treg, FOXP3−CD127+ Tconv but also a major proportion of FOXP3+CD127+ ActTconv, which according to the single-cell transcriptome analysis above resemble cluster 1 and, thus, possess an activated phenotype with immune-suppressive properties." (PMID 33602930, 2021). "In conclusion, our study demonstrates that low-dose decitabine induces degradation of IκBα by β-TrCP through a proteasome degradation pathway, to boost NF-κB activation and thus promotes the proliferation of IFN-γ+CD4+ T cells and enhances the anti-tumor immune activity of CD4+ T cells." (PMID 33791306, 2021). "Previous studies showed that the expression levels of tumor-infiltrating CD4+ T cells, CD8+ T cells, macrophages M1, and natural killer cells may be related to the immune response." (PMID 34745261, 2021). "It remains unclear whether such CD4+ T cell clones are acting by providing help to mobilize other arms of cellular and humoral immunity versus acting directly to kill tumor." (PMID 34910940, 2021). "In addition, CD4+ T cells are also essential to the anti-tumor immune response, which can directly recognize peptide/class II MHC on the surface of cancer cells and kill them." (PMID 34621744, 2021).